SLC40A1 (solute carrier family 40 member 1)
Diseases named in the same sentence as SLC40A1 in open-access papers (continued):
Sharing a sentence is not in itself a finding about the gene and the disease.
Cirrhosis (4 papers, 2016 to 2024). A chronic disorder of the liver in which liver tissue becomes scarred and is partially replaced by regenerative nodules and fibrotic tissue resulting in loss of liver function. "Our results showed that several crucial drivers, including regulators that are potentially associated with the progression of cirrhosis, such as SLC40A1, DAB2, FOLR2, GPAT3, and CDA, were upregulated during fibrosis." (PMID 36845083, 2023).
ischemia (4 papers, 2011 to 2024). A hypoperfusion of the BLOOD through an organ or tissue caused by a PATHOLOGIC CONSTRICTION or obstruction of its BLOOD VESSELS, or an absence of BLOOD CIRCULATION. "Next, we evaluated apoptosis-associated indicators and noted that knockdown of SLC40A1 resulted in a reduction in the discharge of mitochondrial cytochrome c and the quantity of TUNEL staining positive cells induced by ischemia." (PMID 38169607, 2024).
ischemic stroke (4 papers, 2023 to 2025). A stroke disorder caused by obstruction of blood flow to the brain, due to thrombotic (local blood clot formation) or embolic (due to a blood clot or other material traveling from another site) event. "Previous studies have demonstrated that acupuncture can regulate the expression of iron metabolism-related genes (upregulated SLC40A1) in ischemic stroke." (PMID 40552324, 2025). "Among them, FTH1, SLC40A1, NRAS, CD82, and PTPN18 emerged as potential key targets underlying the antiferroptotic effects of acupuncture on ischemic stroke." (PMID 40552324, 2025). "Bioinformatics analysis and RT-qPCR suggested that FTH1, SLC40A1, NRAS, CD82, and PTPN18 might serve as potential key targets underlying the antiferroptotic effects of acupuncture on ischemic stroke." (PMID 40552324, 2025). "The results demonstrated that the expression levels of FTH1, SLC40A1, NRAS, CD82, CD44, and PTPN18 were upregulated in mice with ischemic stroke following acupuncture treatment." (PMID 40552324, 2025). "Moreover, FTH1, SLC40A1, NRAS, CD82, and PTPN18 levels significantly increased after acupuncture in ischemic stroke mice." (PMID 40552324, 2025).
osteoporosis (4 papers, 2021 to 2025). A condition of reduced bone mass, with decreased cortical thickness and a decrease in the number and size of the trabeculae of cancellous bone (but normal chemical composition), resulting in increased fracture incidence. "In our PCR results, only SLC40A1 was identified as a diagnostic marker because its expression in MSCs and monocytes of osteoporosis mice was lower than that in the control." (PMID 37770229, 2023). "Compared with the control group, the expression of HSF1 in MSCs of osteoporosis mice was higher, and the expression of SLC40A1 was lower." (PMID 37770229, 2023). "SLC40A1 is also a hub gene in PPI network, which may be a diagnostic marker of ferroptosis in osteoporosis." (PMID 37770229, 2023). "However, in monocytes, the expression level of CD82 is relatively high in osteoporosis mice, and the expression level of SLC40A1 is relatively low." (PMID 37770229, 2023). "SLC40A1 promotes osteoclast differentiation and is the hub gene of ferroptosis in osteoporosis." (PMID 37770229, 2023). "SLC40A1 may be the hub gene of ferroptosis in osteoporosis by promoting osteoclast differentiation." (PMID 37770229, 2023).
asthma (3 papers, 2023). "GSEA analysis based on the KEGG gene set showed that the terms of the renin-angiotensin system, asthma, histidine metabolism were significantly upregulated in patients with high SLC40A1 expression." (PMID 37740815, 2023). "To date, however, few studies have reported on the relationship between SLC40A1, SLC39A8, CA2, and asthma, or examined the functional roles of the five IMR genes in iron homeostasis imbalance." (PMID 37123407, 2023). "Furthermore, SLC40A1 displayed moderate discriminatory power in distinguishing overall asthma [area under the ROC (AUC) = 0.79] and non-allergic asthma (AUC = 0.70) from controls, and high discriminatory power to distinguish between allergic asthma and controls (AUC = 0.87)." (PMID 37123407, 2023).
chronic kidney disease (3 papers, 2021 to 2024). Impairment of the renal function secondary to chronic kidney damage persisting for three or more months. "Additionally, SLC40A1 showed weak links to chronic kidney disease (P = 1.26e−03), glomerulonephritis (P = 4.43e−02) and blood calcium levels (P = 2.93e−03)." (PMID 38499600, 2024).
Cognitive impairment (3 papers, 2018 to 2026). Abnormal cognition is characterized by deficits in thinking, reasoning, or remembering. "Conversely, overexpression of Slc40a1 or c-Maf attenuated acute mortality and cognitive impairment following CLP, hampered lipid peroxidation and iron deposition, and enhanced antioxidant capacity." (PMID 41804166, 2026). "According to previous studies, the downregulation of Slc40a1 leads to ferrugination and ferroptosis in the brain, with subsequent cognitive impairment in patients with type 1 diabetes." (PMID 36497037, 2022).
mastitis (3 papers, 2020 to 2022). Inflammation of breast tissue during lactation or postpartum due to an obstructed duct or infection. "This suggests that the DNA methylation status and expression of SLC40A1 may change in different directions during mastitis caused by S. uberis compared with E. coli." (PMID 36336691, 2022). "The relative expressions of CITED2 and SLC40A1 in healthy and mastitis cow blood neutrophils were detected using real-time PCR." (PMID 32000686, 2020). "The expression levels of the CITED2 and SLC40A1 genes in mastitis cows were significantly higher in healthy cows (P < 0.05)." (PMID 32000686, 2020). "Among them, SLC40A1 was up-regulated in subclinical mastitis cows compared to healthy cows." (PMID 36204322, 2022). "Notably, the genes SLC40A1 and SLC11A2 were involved in the ferroptosis signaling pathway, and SLC40A1 was up-regulated in subclinical mastitis cows vs. healthy cows." (PMID 36204322, 2022).
metabolic diseases (3 papers, 2022 to 2025).
myocardial infarction (3 papers, 2020 to 2024). Gross necrosis of the myocardium, as a result of interruption of the blood supply to the area, as in coronary thrombosis. "Notably, SLC40A1 upregulation was observed in the ischemic region during the initial phase of myocardial infarction (MI), contributing to iron loss in the cardiomyocytes." (PMID 38169607, 2024). "Importantly, the targeted knockdown of SLC40A1 in cardiomyocytes effectively prevented iron loss and reduced the myocardial infarct size." (PMID 38169607, 2024).
type 1 diabetes (3 papers, 2022 to 2023). "Ferroptosis is associated with type 1 diabetes related cognitive dysfunction, and SLC40A1 mediates ferroptosis in type 1 diabetes." (PMID 36590286, 2022).
allergic asthma (2 papers, 2023 to 2024). A asthma with a basis in a pathological type I hypersensitivity reaction. "A recent study has identified SLC40A1 as a pivotal gene implicated in iron metabolism within airway macrophages, specifically in the context of childhood allergic asthma." (PMID 39364414, 2024). "Reduced SLC40A1 expression may be associated with declined iron levels in the airways of children with allergic asthma." (PMID 37123407, 2023). "Discussion: Overall, these findings reveal the potential role of the iron metabolism-related gene SLC40A1 in the pathogenesis of childhood allergic asthma." (PMID 37123407, 2023). "Taken together, these results implicate the potential role of SLC40A1 in T2 airway inflammation in childhood allergic asthma." (PMID 37123407, 2023). "Among them, SLC39A8, ALOX15, and CA2 showed higher expression, while SLC40A1 and C3 exhibited lower expression in patients with allergic asthma." (PMID 37123407, 2023). "Analysis showed that SLC40A1 exhibited much lower expression in the nasal samples of patients with allergic asthma." (PMID 37123407, 2023). "Taken together, these results suggest that lower SLC40A1 expression may be correlated with reduced iron levels in the airways of children with allergic asthma." (PMID 37123407, 2023). "Given the high correlation between SLC40A1 and T2 airway inflammatory genes, we hypothesized that stratification of children with allergic asthma based on SLC40A1 expression may help predict treatment response and disease severity." (PMID 37123407, 2023). "Given its importance in cellular iron homeostasis, we explored whether SLC40A1 plays a potential role in childhood allergic asthma." (PMID 37123407, 2023). "Thus, further studies on SLC40A1 and other possible biomarkers of childhood allergic asthma are warranted." (PMID 37123407, 2023). "Furthermore, decreased expression of SLC40A1 was closely correlated with reduced iron levels in the airways of children with allergic asthma." (PMID 37123407, 2023). "Our results also showed that SLC40A1 may be involved in changes in airway iron levels in children with allergic asthma." (PMID 37123407, 2023). "Thus, to investigate potential iron metabolism disorder in the airways of children with allergic asthma, we examined iron levels and SLC40A1 expression using qRT-PCR analysis of BAL samples from 18 controls and 28 asthmatic children." (PMID 37123407, 2023).
cardiac insufficiency (2 papers, 2024). "In order to investigated the involvement of SLC40A1 in cardiovascular disease, an analysis was conducted on publicly accessible RNA sequencing data pertaining to human heart failure." (PMID 38169607, 2024).
cystic fibrosis (2 papers, 2013 to 2024). Autosomal recessive disorder caused by pathogenic variants in the CFTR gene (cystic fibrosis transmembrane conductance regulator), which encodes a chloride and bicarbonate channel expressed in epithelial cells, and follow the diagnosis criteria. "Detailed insights are provided into CFTR (ABCC7), an anion channel implicated in cystic fibrosis, and FPN1 (ferroportin 1/SLC40A1), the sole known iron exporter in humans, highlighting their unique roles as ion transporters within ABC and SLC transporter superfamilies." (PMID 39770445, 2024).
dilated cardiomyopathy (2 papers, 2021 to 2024). Cardiomyopathy which is characterized by dilation and contractile dysfunction of the left and right ventricles. "It was observed that the expression of Slc40a1 was higher in dilated cardiomyopathy (DCM) hearts compared to non-failure (NF) hearts." (PMID 38169607, 2024).
Friedreich ataxia (2 papers, 2019 to 2024). An inherited condition that affects the nervous system and causes movement problems. "Importantly, Slc40a1 (ferroportin), involved in iron metabolism linked to Friedreich's ataxia pathology, showed tissue-specific expression changes after Fxn knockdown and partial restoration upon Fxn rescue." (PMID 38846537, 2024). "Tug1 and Slc40a1 emerged as potential blood-based biomarkers, confirmed in the Friedreich’s ataxia knockdown mouse model (one-way ANOVA, P ≤ 0.05)." (PMID 38846537, 2024). "The differential expression of Tug1 and Slc40a1 in intracardiac blood positions these genes as exemplary candidate biomarkers for Friedreich's ataxia, particularly appealing due to the minimal invasiveness required for patient sample collection." (PMID 38846537, 2024). "These collective findings contribute to a deeper understanding of the molecular mechanisms underpinning Friedreich's ataxia and underscore the potential utility of Slc40a1 as a therapeutic marker." (PMID 38846537, 2024). "In the context of these findings, Tug1 emerged as a more suitable biomarker for Friedreich's ataxia compared with Slc40a1." (PMID 38846537, 2024).
hereditary hyperferritinemia-cataract syndrome (2 papers, 2016 to 2022). "In humans, mutations in the iron storage protein FTL (ferritin, light polypeptide) and the iron exporter SLC40A1 (solute carrier family 40 [iron-regulated transporter], member 1) lead to hyperferritinemia-cataract syndrome (OMIM #600886)." (PMID 27141993, 2016).
myocardial ischemia (2 papers, 2021 to 2024). A disorder of cardiac function caused by insufficient blood flow to the muscle tissue of the heart. "We found that knockdown of SLC40A1 significantly decelerated the substantial decline in ATP content following myocardial ischemia." (PMID 38169607, 2024). "Interestingly, knockdown of SLC40A1 significantly attenuated the oxidative stress induced by myocardial ischemia for a duration of 8 hours, as evidenced by DHE staining, MDA level detection, and NADPH content determination." (PMID 38169607, 2024).
renal cell carcinoma (2 papers, 2021 to 2023). "The results showed that FUCA1 was down-regulated and SLC40A1, VSIG4, CRYBB1 and LIPA were up-regulated in renal cell carcinoma and 786-O, and the difference was statistically significant." (PMID 37361571, 2023).
steatosis (2 papers, 2021). Increased lipid within the cytoplasm of cells. "Similarly, SLC40A1, the gene encoding the iron exporter ferroportin, was lower in steatosis and NASH than in HOC, and caeruloplasmin (CP) was decreased in NASH compared to both control groups." (PMID 34869521, 2021). "For the “ferroptosis” pathway three genes were higher (FTL, ATG5, and MAP1C3A) and two were lower in steatosis (SLC40A1 and MAP1LC3C)." (PMID 34869521, 2021).
alcoholic liver cirrhosis (1 paper, 2023). A disorder of the liver characterized by the presence of fibrotic scar tissue instead of healthy liver tissue. "In particular, clusters CD52 mono, C1QC macro, and SLC40A1 macro were more enriched in the PBMCs than in the liver tissues of patients with alcoholic liver cirrhosis." (PMID 36845083, 2023).
arthropathy (1 paper, 2021). Any disorder of the joints. "We found that in the HJV HH, SLC40A1 HH and HH without pathogenic or likely pathogenic variants groups, about half of cases had skin pigmentation, whereas arthropathy occurred in only two cases." (PMID 34583728, 2021).
autism spectrum disorder (1 paper, 2021). A spectrum of developmental disorders that includes autism, and Asperger syndrome. "SLC40A1 has been implicated in the incidence of autism spectrum disorders." (PMID 33834688, 2021).
Bovine mastitis (1 paper, 2022). INFLAMMATION of the UDDER in cows. "On the contrary, the SLC40A1 promoter was identified as hypomethylated with associated up-regulated mRNA expression in blood neutrophils, and consequently considered a candidate biomarker for improving resistance to bovine mastitis induced by E. coli." (PMID 36336691, 2022).
E. coli infection (1 paper, 2020). "Methylation and expression level validation experiments demonstrated that the CITED2 and SLC40A1 expression levels increased, and methylation levels decreased after E. coli infection." (PMID 32000686, 2020).
endometrial cancer (1 paper, 2019). Primary or metastatic malignant neoplasm involving the endometrium (mucous membrane that lines the endometrial cavity). "Nrf2 (Nuclear factor erythroid related factor 2), overexpression of which results in progesterone resistance in endometrial cancer cells, binds to the SLC40A1 promoter and transcriptionally suppressed SLC40A1 expression." (PMID 30813939, 2019). "Interestingly, SLC40A1 was positively correlated with PGR and exhibited reduced expression in endometrial cancer tissues than normal endometrium, indicating a potential relationship between SLC40A1 and PGR dysfunction as well as a mechanism of endometrial cancer proliferation." (PMID 30813939, 2019).
hepatic (1 paper, 2020). "Mutations in iron regulatory gene SLC40A1, which encodes ferroportin, cause a hepatic iron overload hemochromatosis phenotype that negatively affects the intestinal microbiota." (PMID 32635533, 2020).
hyperparathyroidism (1 paper, 2024). Hyperfunction of the parathyroid glands resulting in the overproduction of parathyroid hormone. "This consistency suggests a correlation between elevated expression of PIK3C3 and decreased expression of SLC40A1 with an increased risk of hyperparathyroidism." (PMID 38499600, 2024). "Genetically predicted expression of CMKLR1, PIK3C3, and SLC40A1 retained significant causal associations with hyperparathyroidism risk in GTEx whole blood samples (P < 1.25e−02, inverse-variance weighted methods)." (PMID 38499600, 2024). "Genetically predicted expression of IGSF11, PIK3C3, and SLC40A1 retained significant associations with hyperparathyroidism risk in GTEx thyroid tissue cohort (P < 1.25e−02, inverse-variance weighted methods)." (PMID 38499600, 2024). "Five drug targets (CMKLR1, FSTL1, IGSF11, PIK3C3 and SLC40A1) showed significant causation with hyperparathyroidism in both eQTLGen and GTEx cohorts by MR analysis." (PMID 38499600, 2024). "Moreover, the association between PIK3C3 and SLC40A1 with hyperparathyroidism was corroborated using a parallel analysis in the GTEx database, reinforcing the credibility of the potential drug targets identified in this investigation." (PMID 38499600, 2024). "Targeting PIK3C3 and SLC40A1 may offer effective novel pharmacotherapies for impeding hyperparathyroidism progression and reducing disease risk." (PMID 38499600, 2024). "Consequently, antagonists of PIK3C3 and protagonists of SLC40A1, may represent a novel and robust strategy for reducing the risk of hyperparathyroidism." (PMID 38499600, 2024). "Consequently, we were unable to validate whether protein levels of PIK3C3 and SLC40A1 consistently associated with hyperparathyroidism risk." (PMID 38499600, 2024). "In summary, this cis-eQTL-wide Mendelian randomization and colocalization analysis identified PIK3C3 inhibitors and SLC40A1 antagonists as promising therapeutic targets for hyperparathyroidism." (PMID 38499600, 2024). "This study identifies PIK3C3 and SLC40A1 as potential genetically proxied druggable genes and promising therapeutic targets for hyperparathyroidism." (PMID 38499600, 2024). "Additionally, clinical trials are imperative to evaluate the efficacy and safety of targeting PIK3C3 or SLC40A1 for therapeutic management of hyperparathyroidism." (PMID 38499600, 2024). "Our MR analysis suggested that SLC40A1, a mediator of Fe translating, may be a promising hyperparathyroidism therapeutic targets (eQTLGen odds ratio OR = 0.86, P = 1.31e−05; GTEx whole blood samples OR = 0.52, P = 1.23e−03; GTEx thyroid tissue OR = 0.75, P = 2.89e−137; PPH4 = 0.581)." (PMID 38499600, 2024).
hypochromic anemia (1 paper, 2017). Anemia caused by the reduction of hemoglobin in relation to the red cell volume. "For example, Slc40a1 (ferroportin) is an iron exporter expressed in the YSL, and slc40a1 mutant zebrafish embryos develop hypochromic anemia and iron deficiency." (PMID 28692648, 2017).
idiopathic dilated cardiomyopathy (1 paper, 2024). Decreased function of the heart associated with cardiac enlargement and congestive heart failure, of unknown cause. "Additionally, another analysis revealed elevated mRNA levels of Slc40a1 in idiopathic dilated cardiomyopathy (IDC) and ischemic cardiomyopathy (ICM) hearts." (PMID 38169607, 2024).
Myocardial fibrosis (1 paper, 2024). "The mice with SLC40A1 cardiac knockdown exhibited reduced infarct size and myocardial fibrosis, as shown by Masson trichrome staining, in contrast to the control mice." (PMID 38169607, 2024).
myopia (1 paper, 2017). "Such expression changes were evident, particularly in the late myopia dataset where a wide range of genes linked with oxidative stress were either up-regulated (GPX1, GSTA3, MT-4, APOA1, OTUB, PTGDS, HSPB1, HSPB2) or down-regulated (XHD, SLC40A1, TF, SOD3, HPGDS, BCMO1)." (PMID 28852117, 2017).
Pleural effusion (1 paper, 2005). The presence of an excessive amount of fluid in the pleural cavity. "In addition, expression of the iron transporter, SLC40A1 was generally lower in pleural effusions than in the ascites samples." (PMID 16042759, 2005).